MYC (MYC proto-oncogene, bHLH transcription factor)
Diseases named in the same sentence as MYC in open-access papers (continued):
Sharing a sentence is not in itself a finding about the gene and the disease.
tumor (continued). "This approach may also open avenues for systematically exploring therapy-induced tumor evolution and determining eligibility for trials based on cfDNA-derived CNVs, such as MYC(N) amplifications required for enrollment into the INFORM2 NivEnt trial." (PMID 40579709, 2025). "Irradiation led to a significant decrease in the c-MYC mRNA level in assembloids subjected to 3 Gy X-rays 7 days post-irradiation and in the co-culture of organoid slices and tumor-like cells exposed to 15 Gy X-rays 20 days post-irradiation when compared to the sham-irradiated controls." (PMID 40917877, 2025). "Given previous research indicating that c‐MYC could suppress tumor immunogenicity and promote immune evasion, we further verified that I3A treatment significantly reduced c‐Myc gene expression by q‐PCR." (PMID 40583248, 2025). "The recent phase I clinical trial results of a MYC inhibitor demonstrating safety and anti-tumor activity in solid tumors suggest that c-MYC-targeted therapies may become available for AS patients shortly." (PMID 40666093, 2025). "Similarly, in lung cancer BrM, miR-145-5p is consistently downregulated due to promoter methylation, leading to increased levels of EGFR, OCT-4, and MYC, which enhance tumor migration." (PMID 40016470, 2025). "HDAC inhibitors such as panobinostat disrupt MYC-driven transcription and reduce tumor growth." (PMID 40677711, 2025). "Indeed, MYC deregulation has been proposed to drive tumor development in > 70% of human cancers, including colorectal and breast carcinomas, prostate and liver cancers." (PMID 40000737, 2025). "The Evans Lab used a combination of published scRNA-seq and functional genomics to identify targets in specific subpopulations of tumor cells: a mitotic subpopulation characterized by nucleotide metabolism alterations (Grp3-A) and a progenitor population influenced by MYC hyperactivation (Grp3-B)." (PMID 40471378, 2025). "MYC is a crucial protein in tumor progression, regulating proliferation and apoptosis." (PMID 39928247, 2025). "Thus, the interaction patterns between EZH2 and MYC, as well as the mechanisms by which EZH2 promotes the stabilization of the EZH‐MYC complex, vary across tumor types and warrant thorough investigation." (PMID 39823459, 2025). "Moreover, aberrant MYC expression significantly downregulates MHC Class I molecules thereby reducing the ability of tumor cells to present antigens and be recognized by T lymphocytes." (PMID 39706891, 2025). "Combination of lupeol and enzalutamide markedly reduced viability and migration of cancer stem cells and chemoresistant cells (PTEN-CaP8 and PC3), enhanced cell cycle arrest, suppressed mRNA levels of TCF, AR, c-FLIP, and c-MYC, and inhibited tumor growth in murine model." (PMID 40417209, 2025). "Unlike KC2, KC3 tumours exhibited downregulation of cell cycle‐associated pathways, including mitotic spindle, E2F targets, G2/M checkpoint, MYC targets, mTORC1 signalling and hypoxia‐related pathways." (PMID 41025426, 2025). "We investigated the differences in cancer hallmarks within the tumor TME between the two risk groups and found that the high-risk group was primarily enriched in pathways such as the G2M checkpoint, tumor proliferation signature, DNA replication, MYC targets, and cellular response to hypoxia." (PMID 40496857, 2025). "In parallel, lower MYC activity may attenuate anti-apoptotic gene expression, thereby restraining tumor growth." (PMID 40246846, 2025). "Preclinical mouse models treated with recombinant Lon protease via intratumoral or systemic administration demonstrated significant MYC protein depletion, leading to reduced tumor growth and improved survival rates, particularly in bladder and colorectal cancer models." (PMID 40365020, 2025).
tumor (continued). "Additionally, prolonged CDK8/CDK19 inhibition downregulated the MYC pathway leading to tumour regression." (PMID 40163908, 2025). "Thus, it seems likely that MYC and KAT5/Tip60 have causal roles in regulating protein synthesis and promoting HHT sensitivity in HGG tumor cells." (PMID 40346033, 2025). "The oncoprotein MYC regulates numerous cellular processes, including proliferation, metabolism, cellular senescence, cell metastasis, ribosome and protein biosynthesis, programmed cell death, the immune response, and the tumor microenvironment." (PMID 40290126, 2025). "Consequently, we sorted the MB patient samples according to their known MYC amplification status as is done as part of routine clinical tumor subtyping and then performed immunohistochemistry and immunofluorescence on 45 fresh MB tissues." (PMID 39962590, 2025). "Research has shown that MYC can enhance the sensitivity of tumor cells to glutamine synthetase inhibitors, and researchers believe that MYC can serve as a biomarker for glutamine synthetase inhibitor therapy, the judgement of MYC expression level will provide more treatment opportunities." (PMID 40028341, 2025). "Researchers have found that exosomes in aggressive B-cell lymphomas and plasma cell-derived neoplasms convey oncogenic proteins (including MYC), immunomodulatory chemicals, and miRNAs that help blood vessels grow, make stroma more flexible, and help the cancer cells avoid the immune system." (PMID 40563566, 2025). "Patient ACCC_CRC_15, the only MSI sample in this cluster, also showed an overall trend of under‐activation in the majority of estimated pathway and TF activities, whereas the EGFR signaling cascade and MYC TF were found significantly over‐activated in this POLE‐mutant tumor." (PMID 39876058, 2025). "In contrast, in vivo, blocking MYC expression results in rapid tumor decrease." (PMID 40732268, 2025). "In tumor cells, RTKs and MYC cooperate to promote a malignant phenotype: aberrant activation of RTKs, through overexpression or activating mutations, increases the transcriptional expression of MYC by continuously stimulating the RAS/RAF/MEK and PI3K/AKT pathways." (PMID 40076599, 2025). "It is known that MYC promotes neutrophil infiltration in the external tumor environment." (PMID 40732268, 2025). "Additionally, a wide range of tumor cells with lower complex I expression showed increased MYC dependency." (PMID 40668928, 2025). "Therefore, the efficacy of targeted MYC inhibition in suppressing tumor immune escape can be evaluated by monitoring the transcriptional levels of ENC1." (PMID 40732268, 2025). "Moreover, CBL0137 inhibited the tumor growth of highly aggressive mouse 4T1.2 syngeneic TNBC model in immunocompetent mice by inhibiting the MYC pathway and inducing Type I interferon responses." (PMID 39706891, 2025). "Such an interaction could have important implications for GCN2 in the physiological regulation of MYC and for anti-cancer therapies, particularly those targeting strongly MYC-driven tumours." (PMID 40032489, 2025). "Initiating a series of studies to investigate the potential impact of an MYC inhibitor could offer valuable insights, potentially halting or even reversing tumor progression." (PMID 40076599, 2025). "Previously, we discussed the regulatory role of MYC in tumor immune escape." (PMID 40732268, 2025). "In addition, therapeutic targeting of NPC1 in MYC-driven HCC using AAV8-shNPC1 significantly reduced tumor size and number, with knockdown efficiency validated by Western blotting." (PMID 39762312, 2025). "We therefore performed additional CUT&RUN in human tumor-derived MYC amplified G3MB cell lines." (PMID 41415380, 2025).
tumor (continued). "MYC is frequently amplified in cancer, and its overexpression can drive tumor progression, although excessive MYC levels may also trigger apoptosis." (PMID 40940795, 2025). "Previous studies have suggested that TECs exhibited higher MYC activity and cell cycle progression 13, which might be a potential target for tumor therapy." (PMID 40303332, 2025). "MYC modifies the tumor microenvironment to enable cancer cells to escape from immune surveillance." (PMID 40290126, 2025). "As MYC‐hyperactivated activated cells exhibit enhanced activation of the UPR in various human cancers, which can facilitate tumor survival, the mechanisms underlying this effect remain largely unknown." (PMID 39823459, 2025). "It remains to be tested whether the RNA binding of MYC proteins is important for tumors in an in vivo setting, and whether interfering with the RNA binding capacity of MYC proteins opens new tumor‐specific avenues to target MYC functions." (PMID 40488968, 2025). "FISH analysis of a DLBCL tumor revealed an atypical MYC rearrangement with gain and amplification (66% of nuclei, including 34% with a 3–5+ fusion signal plus one green signal (3-ampF1G) and 32% with 3-ampF2G), a BCL2 rearrangement (73% of nuclei), and an IGH::BCL2 fusion (76% of nuclei)." (PMID 41010038, 2025). "The variations in the regulatory effect of MYC on ferroptosis across different tumor cells may be attributed to the distinct characteristics of oncogenes and the heterogeneity of the TME." (PMID 40732268, 2025). "Therefore, MYC blockade in TECs by nanoparticle-mediated siRNA delivery is an alternative way to normalize tumor vessels." (PMID 40303332, 2025). "In all relapse cases, new subclones arose, but all tumour cells harboured the MYC amplification." (PMID 40335697, 2025). "Furthermore, MYC has the ability to modulate metabolic pathways in tumor cells, enabling them to adapt to environments characterized by low oxygen levels, limited nutrients, and acidity." (PMID 40732268, 2025). "Thus, bypassing these intrinsic tumor suppressor functions of MYC is essential for MYC‐mediated tumorigenesis." (PMID 40488968, 2025). "Deactivating MYC in existing adenocarcinomas immediately reverses stromal changes and causes tumor regression, which is not dependent on CD4+CD8+ T cells but heavily relies on the return of NK cells." (PMID 40732268, 2025). "Complementing these mechanisms, in KRAS-driven malignancies, suppression of the type I interferon (IFN) pathway emerges as a critical mechanism of tumor immune evasion, with pathway inactivation demonstrating strong correlation with concurrent activation of oncogenic signaling networks such as MYC." (PMID 40303413, 2025). "In summary, lncRNAs are pivotal regulators of glucose metabolism in cancer, exerting their influence through direct interactions with transcription factors such as MYC and HIF1α, thereby modulating the expression of key glycolytic enzymes and sustaining tumor metabolic reprogramming." (PMID 41361062, 2025). "MYC and PGC-1α have been linked to metabolic switching and tumor progression/metastasis." (PMID 40607925, 2025). "Second, there is overwhelming evidence that the contribution of MYC to tumorigenesis and its central role as an oncogene is based not only on its cell‐autonomous functions, but also on its non‐cell‐autonomous function in promoting tumor immune privilege." (PMID 40488968, 2025). "In addition, tumor organoids containing genetically modified cells were generated using the Sleeping Beauty transposon system for the induction of c-MYC oncogene overexpression." (PMID 40917877, 2025). "Similarly, the interaction between BRD7 and MYC underscores the balance between tumor suppression and oncogenesis." (PMID 41404623, 2025). "In SyS, MYC is often overexpressed, contributing to aggressive tumor behavior." (PMID 40076599, 2025). "Furthermore, we discovered that ARID1A exerted a tumor-suppressive function through transcriptional suppression of c-MYC and PARP1." (PMID 41049615, 2025).
tumor (continued). "Given the shared mechanisms of tumor progression across cancer types, exploring whether MYC regulates integrin pathways in LMS could uncover novel targets for therapeutic intervention." (PMID 40076599, 2025). "It is well established that aberrant activation of this pathway is a core driver of CRC development, resulting in the movement of β-catenin into the nucleus and the subsequent activation of target genes including c-MYC, and this activation promotes tumor proliferation and metabolic reprogramming." (PMID 41304979, 2025). "Consequently, only the KRASG12V/MYC tumor cells had the ability to grow independently of anchorage, as revealed by soft agar colony formation assays." (PMID 40550880, 2025). "In addition to MAPK, SRC kinases can directly modulate many downstream targets including and c-MYC, related to drug resistance and tumor cell survival." (PMID 40481178, 2025). "Like most oncogenes, the MYC oncogene promoter is hypomethylated in tumor cells." (PMID 39858030, 2025). "Furthermore, recent studies have identified ecDNA amplification of MYC paralogs in a minority of de novo SCLC tumor samples and posttreatment SCLC models, although the prevalence of underlying chromothripsis in such cases remains to be determined." (PMID 39185963, 2025). "KDM4B stabilizes MYC expression through epigenetic regulation, driving tumor progression." (PMID 40565099, 2025). "Given the frequent activation of MYC in a wide range of human cancers, our findings also have implications for understanding how MYC enhances protein biosynthesis to support oncogenic growth and proliferation in the nutrient-competitive environment of a growing tumor." (PMID 40524273, 2025). "WDR5 degraders MS33 and MS67 show promise for MYC‐driven tumor models." (PMID 41049269, 2025). "The increased activity of MXI1 could attenuate MYC-mediated transcription, thereby mitigating MYC-driven metabolic regulation and limiting abnormal tumor cell proliferation." (PMID 40672941, 2025). "Interestingly, substantial copy-number gains of MYC were also observed across tumor types, with the most frequent gains seen in HGSOC tumors." (PMID 39831777, 2025). "In vivo, tumor growth was inhibited, and tumor weight was decreased in MYC‐K412R knock‐in cells." (PMID 40091385, 2025). "Next, we reasoned that AhR and c‐MYC might be the two key factors suppressing tumor immunogenicity, which can be reversed by I3A treatment." (PMID 40583248, 2025). "For instance, MYC-high/HRD tumours may particularly benefit from these combinations, whereas MYC-high/HR-proficient tumours might require alternative/additional targeting strategies." (PMID 41561634, 2025). "Moreover, MYC contributes to tumor growth by interacting with other cellular signaling pathways, including the PI3K/AKT pathway and cyclin-dependent kinases (CDKs)." (PMID 41155227, 2025). "Similarly, preclinical studies have demonstrated that the combination of MYC inhibition with radiotherapy can significantly enhance tumor radiosensitivity and reduce radioresistance, suggesting potential improvements in local tumor control." (PMID 40365020, 2025). "Furthermore, “Hypoxia,” “Glycolysis,” “MTORC1 Signaling,” and “MYC Targets V1” were upregulated in primary tumor tissues and remained elevated in the UPCI-SCC-090 cell line after JQ1 treatment." (PMID 41323280, 2025). "Furthermore, MYC influences the tumor microenvironment by modulating cell–extracellular matrix interactions and immune evasion mechanisms, further complicating therapeutic management." (PMID 40076599, 2025). "This MITF-to-MYC transition may represent a key oncogenic program that supports tumor growth, promotes adaptive survival, and contributes to resistance to targeted therapy." (PMID 40558540, 2025). "Moreover, MYC activation was shown to repress the STING-IFN signaling in various tumor types, including TNBC, resulting in reduced immune cell infiltration and impaired innate anti-tumor immune responses." (PMID 39706891, 2025).
tumor (continued). "Furthermore, it was linked to classic tumor-related pathways, including KRAS, PI3K-AKT-mTOR, and MYC, as well as cell cycle and DNA repair pathways, such as the G2M checkpoint and E2F targets." (PMID 40356980, 2025). "Therefore, the identification of biomarkers capable of predicting prevalent MYC-driven immune escape mechanisms in individual patients and tumor types is essential to guide personalized combinatorial therapeutic strategies." (PMID 40732268, 2025). "This study specifically investigates whether LIN28B promotes EC progression through MYC upregulation and its influence on tumor immune microenvironment remodeling." (PMID 40740861, 2025). "Furthermore, considering the physical proximity of the MYC oncogene to the RECQL4 gene locus, coupled with MYC’s established impact on tumour progression and immune evasion, we included MYC expression as a variable in our multivariate analyses." (PMID 39812592, 2025). "Thus, SPOP appears to exert its tumor-suppressive function, in part, by targeting c-MYC for ubiquitination-mediated proteasomal degradation." (PMID 40521202, 2025). "MYC’s ability to suppress senescence, combined with the pro-survival signaling of RTKs, creates a robust defense against cell death, ensuring the survival of even highly stressed tumor cells." (PMID 40076599, 2025). "Moreover, MYC is involved in the regulation of the AAs metabolism, which correlates with tumor development and progression, since cancer cells have a consistent demand for AAs to provide substrates for energy production." (PMID 41008653, 2025). "Additional emerging areas include gut microbiota composition, which may modulate ICI efficacy; tumor gene expression signatures (e.g., IFN-γ or MYC/E2F pathways); and epigenomic or proteomic markers that reflect immune resistance or tumor aggression." (PMID 40981345, 2025). "The relationship between PA2G4 and MYC remains less clear, particularly in contexts where MYC expression is low, and may depend on tumor subtype." (PMID 41002386, 2025). "In summary, these findings suggest that tumor cells from peripheral ES‐SCLC had a higher expression level of the MYC‐Notch‐non‐NE axis, which might contribute to its chemo‐resistant properties to a significant extent." (PMID 39974662, 2025). "MYC is a widely studied protooncogene that is commonly dysregulated in tumor cells." (PMID 40422212, 2025). "The MYC pathway is a key regulator of cellular growth and proliferation, and is frequently dysregulated in cancer, contributing to uncontrolled cell division and tumor development." (PMID 40018411, 2025). "However, in tumor tissues with high‐ levels of MYC expression and M2‐like macrophages, the proportion of MP‐subtype was centralized and significantly higher than other subgroups." (PMID 39899538, 2025). "Understanding the role of MYC-mediated miRNA dysregulation offers a promising avenue for targeted therapeutic interventions aimed at restoring normal miRNA function and mitigating tumor progression." (PMID 40076599, 2025). "Thus, purine metabolism directly mediates tumor proliferation and development through MYC target genes." (PMID 40699765, 2025). "The MYC further shapes the tumor’s inflammatory environment." (PMID 41011273, 2025). "Collectively, these findings underscore the regulatory role of the TF MYC in modulating glycolytic metabolism in High-M CRC, and highlighted the research significance of cancer-associated fibroblasts (CAFs) as potential interaction partners for tumor cell." (PMID 41234356, 2025). "In our hands, the MYC inhibitor could indeed normalize tumor vessels and exert synergetic effects on enhancing chemotherapy efficiency, consistent with previous studies." (PMID 40303332, 2025). "Specifically, tumours may evade MYC–DDR interventions via restoration of HR, activation of fork-protection pathways, upregulation of alternative transcriptional programmes, or checkpoint adaptation (e.g., PLK1-driven Claspin degradation)." (PMID 41561634, 2025).